BRCA2 (BRCA2 DNA repair associated)
Diseases named in the same sentence as BRCA2 in open-access papers (continued):
Sharing a sentence is not in itself a finding about the gene and the disease.
breast cancer (continued). "All cases had a high risk of developing breast cancer due to a BRCA1 mutation; however, among the controls, there was one BRCA2 mutation carrier and the others had an increased risk due to familial predisposition." (PMID 36293255, 2022). "Population-based prostate and female breast cancer PRS are associated with a wide range of absolute breast and prostate cancer risks for male BRCA1 and BRCA2 carriers." (PMID 34320204, 2022). "The role of BARD1 Cys557Ser varient or BARD1 haplotypes as modifiers of BRCA1/2 associated breast cancer risk was further evaluated in a cohort of 5546 BRCA1 and 2865 BRCA2 mutation carriers." (PMID 35650591, 2022). "The absolute risks of developing breast cancer by age 85 years for BRCA2 carriers was predicted to be 7.7% at the 5th and 18.4% at the 95th PRSER+ distribution percentiles." (PMID 34320204, 2022). "Breast cancers from both BRCA1 and BRCA2 germline mutation carriers have been previously shown to be sensitive to platinum-based chemotherapeutic regimens." (PMID 35857626, 2022). "Hwang reported a median age of 59 years in BRCA1 and 49 years in BRCA2, for any type of breast cancer." (PMID 36349178, 2022). "Deleterious variants in DNA damage response genes, mainly in lung cancer, are associated with a higher mutational burden, as observed in breast carcinomas with DNA damage repair gene variants and in our tumor samples with BRCA1, BRCA2, and PALB2 variants." (PMID 35875117, 2022). "Breast cancer and ovarian cancer are both associated with mutations and/or overexpression/amplification in certain genes (e.g. BRCA1, BRCA2, PIK3C, ERBB2, etc.)and aberrations in related pathways, which exhibits a risk of co-occurrence in women." (PMID 34181736, 2021). "Consistent with its similar molecular functions to BRCA1 and BRCA2, monoallelic germline mutations in PALB2 also confer a high risk of breast cancer and increase the risk of ovarian and pancreatic cancers." (PMID 33893322, 2021). "Our primary goal was to assess the efficacy of various treatments in reducing breast-cancer mortality in the BRCA2 patient population." (PMID 33597716, 2021). "In total, 1,402 BRCA1 and 647 BRCA2 heterozygotes were diagnosed with a metachronous contralateral breast cancer before enrollment in CIMBA." (PMID 34113011, 2021). "Though most breast cancer cases are sporadic, 5–10% of cases are hereditary and mostly related to BRCA1 or BRCA2 gene mutations." (PMID 34290354, 2021). "This dataset includes several different subtypes of breast cancer (118 triple-negative tumors, 293 ER+/HER2- tumors and 71 HER2+ tumors, as well as 36 tumors with BRCA1 and 39 tumors with BRCA2 mutations)." (PMID 34181655, 2021). "Only a small fraction of hereditary breast and/or ovarian cancer (HBOC) cases are caused by germline variants in the high-penetrance breast cancer 1 and 2 genes (BRCA1 and BRCA2)." (PMID 33498765, 2021). "The cumulative lifetime risk of breast cancer that is conferred by pathogenic BRCA1 and BRCA2 variants is estimated to be 65–79% and 61–77%, respectively." (PMID 34771713, 2021). "We have, however, shown that only about half of the BRCA2 999del5 breast cancer cases and pancreatic cancer cases had lost their BRCA2 wild-type allele in the tumor tissue." (PMID 35052422, 2021). "Rare high-risk mutations, particularly in the BRCA1 and BRCA2 genes, explain less than 20% of the twofold familial relative risk (FRR) and account for a small proportion of breast cancer cases in the general population." (PMID 33632172, 2021).
breast cancer (continued). "Founder mutations linked to inherited breast cancer have been reported in BRCA1 and BRCA2 genes in different populations." (PMID 35096615, 2021). "In lung and breast cancer cells, long-term induced inactivation of BRCA2 leads to upregulation of interferon-stimulated genes and activation of the cGAS/STING/STAT pathway, confirming that inactivation of BRCA2 triggers cellular innate immune responses." (PMID 34722771, 2021). "From our database, we also identified all 177 female carriers of P/LPVs in BRCA2 who developed breast cancer." (PMID 33891299, 2021). "A previous study demonstrated that a higher expression of PARP-1, BRCA 1, and BRCA2 resulted in a shorter OS at 10 years in patients with breast cancer." (PMID 34830749, 2021). "We explored publicly available familial breast cancer microarray datasets for phenotypes associated with BRCA1- and BRCA2-related breast tumours." (PMID 34287743, 2021). "The BRCA2 p.I605fs*9 deletion, impacting six breast cancers in current study, was predictive of treatment response of PARP (poly ADP ribose polymerase) inhibitors based on the OlympiAD and EMBRCA trials." (PMID 34203389, 2021). "Our results suggested that MIR3613 locus (13q14.2) located near BRCA2 (13q13.1) in breast cancer and they perhaps had some functional similarity and interactivity." (PMID 33494814, 2021). "Among 73 breast cancer patients with detectable P/LP variants, BRCA1 and BRCA2 accounted for 58 patients (79.5%)." (PMID 33649982, 2021). "Similar to its impact on BRCA-knockout cells, MED12 depletion promoted olaparib and cisplatin resistance in BRCA1-mutant MDA-MB-436 breast cancer cells and BRCA2-mutant PEO1 ovarian cancer cells." (PMID 34871431, 2021). "The secondary exploratory aim of this study was to evaluate the association of germline BRCA1/BRCA2 mutations with somatic PIK3CA mutations in a cohort of young and postmenopausal patients with breast cancer." (PMID 34287479, 2021). "In the present study, we show that histologically normal breast tissue from younger women who are susceptible to breast cancer, as a result of harboring a germline mutation in BRCA1, BRCA2 or PALB2 genes, exhibits hallmarks of accelerated aging." (PMID 35187501, 2021). "Drugs that target this pathway have been clinically validated in patient subgroups, such as the use of PARP (poly ADP-ribose polymerase) inhibitors to treat BRCA1/BRCA2 mutant breast cancer patients." (PMID 33832493, 2021). "Second, some clinical risk factors like Ki-67 index and BRCA1- and BRCA2- related mutation as well as high 21-Gene Recurrence Score (21-GRS) which have been proved to be related to worse OS in patients with breast cancer were unavailable in the SEER database." (PMID 35116010, 2021). "The most well-known high-penetrance breast cancer predisposition genes are BRCA1 and BRCA2, each predicting 84% and 56% lifetime breast cancer risk." (PMID 34574977, 2021). "Interestingly for BRCA2 gene, 6 breast cancer patients were double heterozygous carrying the two deleterious mutations c.632-1G>A and c.1310_1313delAAGA, and 4 other unrelated patients carried only the c.1310_1313delAAGA mutation including one male breast cancer (MBC)." (PMID 34490083, 2021).
breast cancer (continued). "Multiple studies have demonstrated the estimated lifetime breast cancer risk for BRCA1 carriers to be about 80% and 70% for BRCA2 carriers." (PMID 34573353, 2021). "The cumulative incidence of breast cancer at the age of 70 years in men is 1% for BRCA1 mutation and 7% in BRCA2 mutation." (PMID 33996049, 2021). "The strengths of this study are the combined analysis of germline BRCA1/BRCA2 and somatic PIK3CA mutations in a group of postmenopausal and young patients with breast cancer." (PMID 34287479, 2021). "Only one each BRCA1 and BRCA2 deaths in carriers were breast cancer related in women on MRI screening (2/38)." (PMID 34312777, 2021). "Increasing numbers of first-degree and second-degree family members with breast cancer were associated with higher odds of having a BRCA1 (OR, 1.93; 95% CI, 1.68-2.21; P < .001) and a BRCA2 variant (OR, 1.52; 95% CI, 1.26-1.85; P < .001)." (PMID 33646313, 2021). "The cumulative risk estimates for developing breast cancer by age 80 are 70–90% for carriers of BRCA1 pathogenic variants and 60–70% for BRCA2 carriers." (PMID 34290354, 2021). "BRCA2 is known for its involvement in breast cancer and ovarian cancer via the homologous recombination pathway, which is essential for repairing damaged DNA." (PMID 33889545, 2021). "Of all breast cancer cases, 5–10% have a strong hereditary background and a recent study has estimated the prevalence of pathogenic variants in BRCA1 and BRCA2 among unselected breast cancer patients to be about 4.5%." (PMID 34529195, 2021). "The personal or family history of mammary malignancies and inherited genetic mutations in breast cancer susceptibility genes, mostly BRCA1 (BRCA1 DNA Repair Associated) and BRCA2 (BRCA2 DNA Repair Associated), account for 5% to 10% of breast tumor cases." (PMID 33498667, 2021). "The breast cancer susceptibility factors BRCA1 (FANCS) and BRCA2 (FANCD1) are key players in homologous recombination and act downstream of the FANCI/FANCD2 complex to repair the DSBs formed by ICLs processing." (PMID 34359655, 2021). "Olaparib is used in the clinic for the breast cancer patients with mutated BRCA1 and/or BRCA2 where the HR DNA repair is impaired." (PMID 34572735, 2021). "Male breast cancer is a rare disease accounting for less than 1% of all breast cancer cases and it was previously shown that nearly 90% of MBC arising in BRCA mutation carriers are found to harbor a BRCA2 mutation." (PMID 34490083, 2021). "According to the results of an international BRCA1/2 cohort study, the cumulative risk of developing breast cancer among BRCA1/2 variant carriers reaches approximately 70% by the age of 80 (72% in BRCA1 variant carriers and 69% in BRCA2 variant carriers)." (PMID 35008774, 2021). "The penetrance or cumulative lifetime risk of developing breast cancer is estimated at 72% for BRCA1 and 69% for BRCA2 pathogenic variant carriers." (PMID 34072979, 2021). "Deleterious germline variants in ATR and ATM were also associated with HRD phenotype in breast cancer, ATM in prostate, lung, and stomach cancers, and BRCA2 in stomach cancers." (PMID 34572800, 2021). "We showed significant albeit modest associations among both BRCA1 and BRCA2 heterozygotes between the PRS and contralateral breast cancer risk." (PMID 34113011, 2021). "Nevertheless, BRCA1 carriers were more likely to be triple negative breast cancer compared to BRCA2 carriers (p=0.002) and BRCA2 carriers were more likely to be luminal B breast cancer tumors (p=0.000078)." (PMID 34490083, 2021). "BRCA1 and BRCA2 heterozygotes under age 40 at first breast cancer, at the 5th and 95th percentile of the PRS, differed by 10% in 10-year contralateral breast cancer risk." (PMID 34113011, 2021).
breast cancer (continued). "In Jamaica, we found a 5.5% (10 of 183) rate of inherited breast cancer with germline variants in BRCA1, BRCA2, PALB2, STK11, and NBN genes." (PMID 33646313, 2021). "Genetic predisposition accounts for 10–30% of breast cancer cases, and its rate of finding germline pathogenic variants in BRCA1 or BRCA2 (gBRCA) was 3–5%." (PMID 33649982, 2021). "Initial studies using the three FDA-approved drugs showed selective killing of BRCA1-mutated breast cancer cells, BRCA2-mutated ovarian cancer cells (PE01), and BRCA1-mutated ovarian cancer cells (UWB1.289)." (PMID 33784323, 2021). "In conclusion, we recommend that a molecular test for BRCA1, BRCA2, PALB2 and CHEK2 recurrent mutations should be offered to male breast cancer patients in Poland." (PMID 34461861, 2021). "We describe the first reported case of three concurrent pathogenic germline variants in BRCA1, BRCA2, and CHEK2 associated with inherited breast cancer in an individual." (PMID 33507482, 2021). "An important correlation also exists between germ-line mutations in breast cancer susceptibility genes 1 and 2 (BRCA1 and BRCA2), which are associated with a 40–85% lifetime breast cancer risk, and AR structure and transcriptional activity." (PMID 35008851, 2021). "The majority (approximately 80%) of breast cancers arising in BRCA1 germline mutation are TNBC, while 11–16% of all TNBC harbor BRCA1 or BRCA2 germline mutations." (PMID 34503097, 2021). "In Chinese breast cancer patients, PIK3CA somatic mutations were detected in 14% and 43% of the patients harboring germline BRCA1/BRCA2 mutations (vs. wild type carriers), respectively." (PMID 34287479, 2021). "Estimated cumulative risk for development of breast cancer in carriers of BRCA1 and BRCA2 mutation is 72% and 69%, respectively, up to the age of 80 years." (PMID 33540843, 2021). "In the current study, we evaluated the frequency of 20 recurrent mutations in six genes (BRCA1, BRCA2, CHEK2, PALB2, NBN and RECQL) in 165 men diagnosed with breast cancer in Poland." (PMID 34461861, 2021). "BRCA2 carriers were diagnosed earlier with breast cancer at 57 years compared to BRCA1 carriers at 62 years." (PMID 34575694, 2021). "We estimated the prevalence of 20 alleles in six genes (BRCA1, BRCA2, CHEK2, PALB2, NBN, RECQL) in 165 Polish male breast cancer patients." (PMID 34461861, 2021). "Any family history of breast cancer was associated with both P/LP BRCA1 variant (OR, 4.87; 95% CI, 2.82-8.42; P < .001) or a P/LP BRCA2 variant (OR, 3.07; 95% CI, 1.40-6.71; P = .005)." (PMID 33646313, 2021). "The European Society of Breast Cancer Specialists (EUSOMA) mentions that approximately 3% of all breast cancers occur in women with BRCA1 and BRCA2 deleterious mutations." (PMID 33859904, 2021). "For several decades, physicians have modeled genetic susceptibility to breast cancer with BRCA1 and BRCA2 variants to characterize women’s predisposition to breast cancer incidence and recurrence." (PMID 34038146, 2021). "There are other high penetrance gene mutations associated with breast cancer, but BRCA1 and BRCA2 are best elucidated." (PMID 33996049, 2021). "Breast cancer 1 plays a critical role in the response to DNA damage; additionally, BRCA2 is essential for maintaining genome integrity." (PMID 33854442, 2021). "Existing studies seem to favor BRCA1/BRCA2 as having little effect on the prognosis of breast cancer." (PMID 34198652, 2021).
breast cancer (continued). "The most common germline mutations associated with breast cancer are in breast cancer susceptibility genes 1 and 2 (BRCA1 and BRCA2), which encode proteins responsible for double-stranded DNA repair." (PMID 34441794, 2021). "In total, 61 BRCA1, 128 BRCA2 and 11 both BRCA1 and BRCA2 genes associated breast cancer patients’ data were used to train the system using Mamdani’s Fuzzy Inference Method and Feed-Forward Neural Network Method as the model softwares on MATLAB." (PMID 34828379, 2021). "Estimates show that 5–10% of breast cancer cases are hereditary, caused by genetic variants in autosomal dominant genes; of these, 16% are due to germline mutations in the BRCA1 and BRCA2 genes." (PMID 33499154, 2021). "The effects on these subgroups are subtle, contrary to mutations such as in breast cancer type 1 (BRCA1) & breast cancer type 2 (BRCA2) that, when present, predict an approximate 70% chance of the development of breast cancer by the age of 80." (PMID 33667227, 2021). "The best known and most penetrant germline genetic mutations responsible for ovarian cancer are in the tumor suppressor breast cancer susceptibility genes 1 and 2 (BRCA1 and BRCA2), which are noted in 13–20% of ovarian cancers." (PMID 33419231, 2021). "Two recent studies in 64 791 and 113 927 women respectively confirmed that mutations in HR genes BRCA1, BRCA2, PALB2, BARD1, RAD51C and RAD51D correlate with increased breast cancer incidence." (PMID 34316706, 2021). "PBSO further gives a reduction in ovarian cancer specific mortality of 95% and in breast cancer specific mortality of 42% The risk reduction in breast cancer is more pronounced for BRCA1 mutation carriers than BRCA2 mutation carriers." (PMID 33996049, 2021). "In this cohort of postmenopausal breast cancer patients, 10.2% harbored pathogenic germline BRCA1/BRCA2 variants; 11.7% of these patients had at least one family member who was affected with breast, ovarian, prostate, or pancreatic cancer." (PMID 34287479, 2021). "There is a difference in overall survival between breast cancer patients with BRCA1 and BRCA2 mutation." (PMID 33996049, 2021). "Breast cancer was one of the associated cancers in families of very young ALL patients, and the Fanconi anemia-BRCA2 pathway is a known risk factor for childhood ALL2,21." (PMID 34117277, 2021). "Double heterozygotes were more likely to be diagnosed with breast cancer compared to women with only one deleterious BRCA pathogenic variant (68.1% vs. 52.0% for BRCA1, p = 0.002; 67.4% vs. 50.4% for BRCA2, p = 0.002)." (PMID 33507482, 2021). "High mammographic density (MD) is a significant risk factor for the development of breast cancer, as is inheritance of mutations in BRCA1 or BRCA2 tumour suppressor genes." (PMID 34209669, 2021). "Hereditary breast and ovarian cancer (HBOC) risk has been traditionally linked to germline pathogenic variants (PVs) in breast cancer 1 and 2 genes (BRCA1 and BRCA2)." (PMID 33498765, 2021). "In the present study, we first found a widespread loss of miR-3613-3p DNA fragment (13q14.2) in breast cancer patients genome, which located near the famous tumor suppressor genes RB1 (13q14.2) and BRCA2 (13q13.1)." (PMID 33494814, 2021). "The important factors increase a man’s risk of breast cancer are: older age, BRCA2/BRCA1 mutations, increased estrogen levels, Klinefelter syndrome, family history of breast cancer, and radiation exposure." (PMID 34503097, 2021).